GREM1 (gremlin 1, DAN family BMP antagonist)
Diseases named in the same sentence as GREM1 in open-access papers (continued):
Sharing a sentence is not in itself a finding about the gene and the disease.
mesothelioma (10 papers, 2017 to 2022). A usually malignant and aggressive neoplasm of the mesothelium which is often associated with exposure to asbestos. "We have previously shown high expression of FBN1 and FBN2 as well as MMP2 in association with high GREM1 expression in JP5 cells as well as in other mesothelioma cells." (PMID 29968778, 2018). "GREM1-induced Slug expression is linked to the migration and invasive growth of mesothelioma cells." (PMID 32141512, 2020). "A high expression in GREM1 has been demonstrated in mesothelioma cells, which induces mesothelioma cell growth." (PMID 31143092, 2019). "Moreover, in vivo mesothelioma xenograft experiments indicated that GREM-1 overexpressing tumors were more vascular and had a metastatic potential." (PMID 35203511, 2022). "Interestingly, the expression of GREM1 was significantly reduced by pirfenidone in the two different mesothelioma cell lines, suggesting a mechanism by which pirfenidone can rescue BMP-pathway activity." (PMID 29968778, 2018). "Stromal GREM1 expression has been demonstrated not only in BCCs but also in many invasive carcinomas, such as carcinomas of the esophagus, pancreas, colon, lung, breast, and mesotheliomas." (PMID 28346486, 2017). "GREM1 also activates Slug to increase EMT and the growth of mesothelioma cells." (PMID 32141512, 2020).
diabetes (9 papers, 2013 to 2025). "Moreover, the downregulation of GREM1 showed an association with the occurrence of associated pathologies (diabetes and hypertension)." (PMID 36768749, 2023). "Our in vivo data showing coincident grem-1 overexpression with the development of renal damage, support the idea of GREMLIN as a key VEGFR2/ligand mediator of renal damage progression in diabetes." (PMID 31973092, 2020).
gastric cancer (9 papers, 2016 to 2025). A primary or metastatic malignant neoplasm involving the stomach. "Loss of H3K27 methylation of the GREM1 gene has been identified as one potential mechanism of GREM1 mRNA upregulation in CAFs in gastric cancer." (PMID 40277903, 2025). "Note also that the role of GREM1 itself is well established in the onset and prognosis of colorectal and gastric cancers." (PMID 37996550, 2023). "Clinical studies to examine the association of mRNA expression of GREM1, BAG2, OLFM4, TRIP6 and MAGE-A9 and OS in patients with intestinal or diffuse subtype of gastric cancer using different chemotherapeutic agents need to be done." (PMID 34885041, 2021). "Hence, the exact role of GREM1 in gastric cancer still needs to be defined." (PMID 34885041, 2021). "Overexpression of BAG2, GREM1, OLFM4, and TRIP6 in the diffuse subtype of gastric cancer on IHC as compared to the intestinal subtype suggests a role of these proteins in the pathogenesis and progression of the diffuse subtype." (PMID 34885041, 2021). "The candidate proteins BAG2, GREM1, OLFM4, TRIP6, and MAGE-A9, were shown to be differentially expressed and validated using IHC in the diffuse and intestinal subtypes of gastric cancer." (PMID 34885041, 2021). "Since GREM1 functions as an antagonist against both BMP2 and BMP4, its upregulation would result in a general inhibition effect to the BMP signaling pathways in gastric cancer." (PMID 29720137, 2018). "Although GREM1, BAG2, OLFM4, TRIP6 and MAGE-A9 have all been previously implicated in tumor progression and metastasis, they have not been linked to intestinal or diffuse subtypes of gastric cancer." (PMID 34885041, 2021).
glioblastoma (9 papers, 2018 to 2025). The most malignant astrocytic tumor (WHO grade IV). "siRNA-mediated knockdown of GREM1 in U87-MG glioblastoma cells induced cell cycle arrest and apoptosis, and abolished TGF-β1-mediated activation of SMAD2 signaling, inhibiting EMT in these cells." (PMID 40277903, 2025). "We confirmed the presence of GREM1 on BC-specific EVs, validated through immuno-electron microscopy, and its distinctive expression patterns among different BC cell lines and glioblastoma-derived EVs." (PMID 40069570, 2025). "This is consistent with a previous report that found Grem1 promotes proliferation and suppresses astrocyte differentiation of cancer stem cells in glioblastoma." (PMID 34184027, 2021). "Finally, it has been demonstrated in glioblastomas that cancer stem cells express GREM1 to counteract BMP-driven differentiation, and promote their self-renewal." (PMID 30563495, 2018). "The authors also analyzed plasma samples collected from GBM patients following 5-ALA administration, which revealed that PpIX-positive EVs were enriched in glioblastoma-associated transcripts, specifically Gremlin 1 (GREM1)." (PMID 41157189, 2025). "On the other hand, GREM-1 knockdown reduced the cell viability, promoted apoptosis, and inhibited the migration, invasion, and EMT process in the glioblastoma cell line U87-MG." (PMID 35203511, 2022). "Using a BRET-based approach monitoring activation of G-protein isoforms, GREM1 failed to activate any G-protein in either HEK293 or U251 glioblastoma cells, suggesting that GREM1 is not binding to a GPCR at the plasma membrane (data not shown)." (PMID 41033552, 2025). "Analysis of GREM1 expression on the surface of BC cell EVs by immuno-electron microscopy using a GREM1 antibody confirmed higher expression of GREM1 on BT-549 EVs compared to MCF7 EVs and, interestingly, lower expression on glioblastoma U87MG-derived EVs compared to the former two." (PMID 40069570, 2025).
Obesity (9 papers, 2021 to 2026). Accumulation of substantial excess body fat. "We hypothesized that white tea supplementation would be associated with reduced GREM1 expression and improved metabolic parameters in a high-fat diet–induced obesity model." (PMID 41596576, 2026). "Circulating and tissue levels of GREM1 are elevated in individuals with obesity, type 2 diabetes mellitus (T2DM), and non-alcoholic fatty liver disease (NAFLD)." (PMID 41596576, 2026). "The experimental data from our study suggests a potential involvement of the role of GREM1 as a central regulator in the pathophysiology of obesity, as reported in the literature." (PMID 41596576, 2026). "In summary, the primary finding of this study was the association between white tea supplementation and alterations in GREM1 expression in a high-fat diet–induced obesity model." (PMID 41596576, 2026). "Elevated GREM1 levels in obesity have been shown to impair this process, contributing to reduced energy dissipation and enhanced lipid accumulation." (PMID 41596576, 2026). "Some potential biomarkers for obesity include genes like early growth response 2 (EGR2), gremlin-1 (GREM1), and neuropeptide Y1 receptor (NPY1R)." (PMID 40186666, 2025). "Gremlin 1 (GREM1), a bone morphogenetic protein (BMP) antagonist, is increasingly recognized as a key regulator of adipose tissue dysfunction and impaired thermogenesis in obesity." (PMID 41596576, 2026). "Increased GREM1 gene expression in visceral adipose tissue, alongside the highest serum GREM1 levels observed in the HFD group, may suggest that GREM1 is activated both locally and systemically in obesity-related pathophysiological processes." (PMID 41596576, 2026).
colitis (8 papers, 2021 to 2025). Inflammation of the colon. "Particularly in SETD2-deficient colitis, the therapeutic effect of targeting deliver Grem1 is significantly higher than that of DSS-induced colitis." (PMID 39990215, 2025). "Besides, we also explored that loss of Setd2 in ISCs exacerbates DSS-induced colitis in mice and targeted delivery of Grem1 by AT-MSCs shows higher efficacy in Setd2-deficient colitis." (PMID 39990215, 2025). "Next, we successfully delivered BMP inhibitor Grem1 and anti-inflammatory factor IL-10 to inflammatory colon tissues by AT-MSCs and reduced experimental colitis." (PMID 39990215, 2025). "Leedham and collaborators analyzed the role of BMP signaling in intestinal regeneration and showed a reduction of epithelial BMP-4 production and an increase in stromal GREM-1 production during colitis." (PMID 40319019, 2025). "Targeted delivery of Grem1 reduced colitis by promoting intestinal stem cell regeneration and enhancing mucosal regenerative capacity." (PMID 39990215, 2025). "For instance, Grem1 and Rspo3 reportedly increased PDGFRαlo cells during colitis-induced conditions." (PMID 38540281, 2024). "For example, production of BMPs by PDGFRαhi fibroblasts is reduced, while Grem1, Rspo3 and Sfrp1 are induced in all PDGFRαlo cells during acute colitis, indicating a shift towards the support of ISC proliferation." (PMID 36032088, 2022). "Having identified profound upregulation of a single BMP antagonist inmouse DSS colitis models, we used a dual morphomolecular approach tocharacterize the Grem1-expressing cell population(s)." (PMID 33819486, 2021). "Moreover, DSS-induced colitis increased fgf10, Vegf, Wnt2b, Grem1, and Rspo1 expressions in CD34+ cells." (PMID 38540281, 2024). "For Grem1-AT-MSC groups, the efficacy indexes of the Setd2ISC-KO colitis mice after treatment were statistically significantly higher than Setd2f/f mice." (PMID 39990215, 2025). "Together, these data show acomparable pattern of BMP pathway suppression after barrier breach in human andmouse, with correlative stromal upregulation of GREM1 in humanIBD and Grem1 in mouse DSS colitis tissue." (PMID 33819486, 2021). "Indeed, IL-1 signaling in Grem1+ cells is sufficient and necessary for recovery after DSS-induced colitis." (PMID 38203319, 2023).
pancreatic neuroendocrine tumor (8 papers, 2015 to 2025). Pancreatic endocrine tumor, also known as pancreatic neuroendocrine tumor (PNET), describes a group of endocrine tumors originating in the pancreas that are usually indolent and benign, but may have the potential to be malignant. "GREM1 was also overexpressed in malignant mesothelioma, pancreatic neuroendocrine tumors and hepatocellular carcinoma associated with hepatitis C infection." (PMID 35883579, 2022). "Stromal-derived Grem1 has also been implicated within the unique tumor microenvironment of other cancers including mesothelioma, pancreatic neuroendocrine tumors, mammary, uterine, cervical, and kidney tumors." (PMID 32756430, 2020). "In contrast, increased GREM1 expression in pancreatic neuroendocrine tumors is associated with an increase in patient progression-free survival and has been reported as a predictor of positive outcomes." (PMID 32756430, 2020). "For example, a study in 2013 identified that GREM1 expression correlated with increased angiogenesis and progression-free survival in patients with pancreatic neuroendocrine tumors, suggestive of a tumor suppressor role for GREM1." (PMID 40277903, 2025). "Chen and colleagues suggested that GREM1 is a prognostic marker for better survival in patients with pancreatic neuroendocrine tumors (NETs)." (PMID 37615860, 2023). "Angiogenesis is regulated by GREM1 to elevate the microvessel density in pancreatic neuroendocrine tumors." (PMID 36091126, 2022). "The expression of GREM1, a bone morphogenetic protein antagonist, correlates with increased angiogenesis in humans with pancreatic neuroendocrine tumors; whereas, the knock-down of GREM1 in human HK–2 cells increases BMP7 signaling activity." (PMID 26445145, 2015). "These authors describe a tumor suppressor role for GREM1 in pancreatic NETs, although this conclusion relies solely on IHC data and not the more robust, quantifiable, and selective detection of Grem1 mRNA." (PMID 37615860, 2023).
adenoma (7 papers, 2012 to 2025). A neoplasm arising from the epithelium. "In contrast, conventional tubulovillous adenomas arise through constitutive epithelial wnt activation as a consequence of initiating APC mutation in crypt base columnar cells, and have only stromal expression of Grem1." (PMID 40467544, 2025). "In 2020, CRISPR/Cas9 technology was extensively exploited to construct human serrated adenoma models elucidating RSPO fusion genes and GREM1 overexpression in CRC." (PMID 39054866, 2024).
Insulin resistance (7 papers, 2022 to 2026). Increased resistance towards insulin, that is, diminished effectiveness of insulin in reducing blood glucose levels. "White tea administration was associated with lower GREM1 expression and serum levels, accompanied by reductions in weight gain and insulin resistance." (PMID 41596576, 2026). "In animal models fed a high-fat diet (HFD), GREM1 expression increases significantly in visceral adipose tissue, which is associated with impaired glucose tolerance and increased insulin resistance, even in the absence of significant weight gain." (PMID 41596576, 2026). "Consistent with its known mechanism of action, orlistat administration improved insulin resistance but did not significantly alter GREM1 expression or circulating levels, suggesting that its metabolic effects are largely independent of the GREM1–BMP4 axis." (PMID 41596576, 2026).
liver fibrosis (7 papers, 2019 to 2025). "Accumulating evidence has shown that Grem1 can induce inflammation and is implicated in many pathogenic mechanisms and diseases, such as heart, lung, and liver fibrosis, as well as osteogenesis, angiogenesis, and cancer." (PMID 35440754, 2022). "Grem1 is believed to have a variety of functions, such as regulating the development of the skeleton, kidney, retina, and lung, and is involved in the pathogenic mechanisms of lung and liver fibrosis, osteogenesis, angiogenesis, and cancer." (PMID 35440754, 2022). "Validation of GREM1 expression in human and rat metabolic dysfunction-associated steatohepatitis (MASH) liver fibrosis." (PMID 39361025, 2024). "Other known genes upregulated by GREM1 include genes associated with hyperglycemia (DUSP639), NAFLD/NASH (FABP140,41, LYZ42 and TP53INP143), liver fibrosis (CTHRC144) and hepatocellular carcinoma (LPAR645 and CCL1546)." (PMID 35995996, 2022). "In addition, proceeding study reported that lipid metabolism in activated hepatic stellate cells is enhanced during liver fibrosis; thus, we measured the lipid droplet content in GREM1-treated fibroblasts." (PMID 33967807, 2021). "Previous studies have established Grem1 as a critical regulator in the development of NAFLD and liver fibrosis by its inhibition of bone morphogenetic protein (BMP) signaling." (PMID 39851554, 2025).
polyposis (7 papers, 2013 to 2025). "It seems as if patients with mutations in APC, BMPR1A, SMAD4 and GREM1 can have similar polyposis phenotypes but carriers of GREM1 mutation with HMPS might not have the same risk for extra-colonic disease as patients with BMPR1A mutations and HMPS." (PMID 27696107, 2017). "Anti-GREM1 reversed these changes, highlighting a potential strategy for preventing polyposis in patients with HMPS." (PMID 40467544, 2025). "Overexpression of GREM1 in CRC patients is associated with tumour proliferation, polyposis and poor prognosis." (PMID 40506516, 2025). "Together, these data show that aberrant epithelial Grem1 expression induces reversible intestinal architectural change and that the mixed polyposis phenotype can be both prevented and reversed through sequestering inhibition of Grem1." (PMID 40467544, 2025). "The data gathered to date indicate that GREM1 duplications may occur in individuals with or without polyposis." (PMID 33806975, 2021).
prostate carcinoma (7 papers, 2004 to 2025). A carcinoma that arises from epithelial cells of the prostate gland. "GREM1 signaling via FGFR1 → MAPK has been identified as a key signaling pathway regulating lineage plasticity in castration-resistant prostate cancer." (PMID 40277903, 2025). "In particular, GREM1 has been found that anti-GREM1 therapeutic antibody has a strong tumor-inhibitory effect on prostate cancer and CRC tumoroid." (PMID 37726845, 2023). "Previous research revealed a tight connection between GREM1 and the incidence and metastasis of numerous tumor types involving breast, lung, and prostate cancer." (PMID 37605239, 2023). "A novel anti-GREM1 neutralizing antibody generated by this group demonstrated anti-tumor effects in prostate cancer cell-derived tumors in nude mice." (PMID 37615860, 2023). "A demonstration of GREM1-mediated activation of FGFR1 in vivo (independent from its inhibitory effect on BMP signaling) in prostate cancer would strengthen the argument that GREM1 promotes prostate cancer progression by activating FGFR1." (PMID 37615860, 2023). "Although lack of drug information targeting GREM1, studies have been found that specific anti-GREM1 therapeutic antibody has a strong tumor-inhibitory effect on prostate cancer and CRC tumoroid." (PMID 37726845, 2023). "In addition, targeting GREM1 using a neutralizing antibody produced a tumor-inhibiting effect in a mouse model of castration-resistant prostate cancer." (PMID 40277903, 2025). "Moreover, GREM1 has been described to bind and signal to vascular endothelial growth factor receptor (VEGFR) and stimulate angiogenesis, as well as epidermal and fibroblast growth factor receptor (EGFR and FGFR) to elicit tumor-promoting effects in breast and prostate cancer, respectively." (PMID 37615860, 2023).
hepatocellular carcinoma (5 papers, 2020 to 2025). A malignant tumor that arises from hepatocytes. "Compared to NTA-MSCs, TA-MSCs from gastric cancer, lung cancer, pancreatic cancer and hepatocellular carcinoma (HCC) exhibit a notable elevation in cytokines like IL-6, IL-8 and TGF-β, along with genes including MMP1, S100A4, GREM1, and LOXL2, all of which are associated with tumorigenesis." (PMID 40676710, 2025).
Osteopenia (5 papers, 2020 to 2025). Osteopenia is a term to define bone density that is not normal but also not as low as osteoporosis. "In previous studies, Grem1 overexpression inhibits osteoblastogenesis and causes osteopenia in mice." (PMID 33029507, 2020). "Conversely, Grem1, a BMP antagonist, was upregulated in Tnfaip6-deficient mMSCs, in line with its known inhibitory role in osteoblastogenesis and association with osteopenia." (PMID 41394803, 2025). "In mice, conditional deletion of Grem1 in osteogenic linage cells enhances osteoblastic activity and bone formation, whereas skeletal overexpression of Grem1 decreases the number and function of osteoblasts, leading to osteopenia and spontaneous fractures." (PMID 36443839, 2022). "However, osteopenia, particularly at the vertebral region, and skeletal abnormalities were demonstrated in Grem1 null mice in which Grem1 was globally inactivated." (PMID 33029507, 2020).
osteosarcoma (5 papers, 2011 to 2024). A usually aggressive malignant bone-forming mesenchymal neoplasm, predominantly affecting adolescents and young adults. "When osteosarcoma cells are overexpressed with GREM1, they are inhibited from proliferating, migrating, invading, and angiogenically growing." (PMID 38970064, 2024). "Furthermore, GREM1 has been suggested to decrease the metastatic potential of osteosarcoma." (PMID 32328030, 2020).